LDHA (lactate dehydrogenase A)
Diseases named in the same sentence as LDHA in open-access papers (continued):
Sharing a sentence is not in itself a finding about the gene and the disease.
cancer (continued). "The levels of Pan Kla and histones H3K9la and H3K56la in liver cancer were positively correlated with the expression of cancer malignancy markers (the stemness marker CD133, the proliferation marker BCL2, the cancer cell proliferation marker Ki67, and the glycolysis enzyme LDHA)." (PMID 36686771, 2022). "However, in another study, LDH activity was shown to be inhibited by LDHA K5 acetylation, which decreased proliferation and migration in cancer cells." (PMID 35090076, 2022). "In preclinical studies, it has been shown that inhibition of LDHA may have potential application in cancer therapy." (PMID 35628385, 2022). "Notably, oxidative cancer cells are less sensitive to LDHA inhibitors, while some glycolytic cancer cells will compensate for the inhibition of glycolysis by OXPHOS and become resistant to LDHA inhibitors." (PMID 36230492, 2022). "A previous study found that enforced KLF4 expression could decrease LDHA expression in cancer cells, thereby forming a KLF4/LDHA signaling pathway to regulate aerobic glycolysis." (PMID 35757505, 2022). "There was an upregulation of genes participating in glucose transport, mainly GLUT6, the glycolytic enzymes HK1 and HK2, the phosphofructokinase PFKFB3, the enolases ENO3, and ENO2, and the lactate dehydrogenase LDHA, similar to the Warburg effect in cancer cells." (PMID 35163725, 2022). "All these results suggested that glycolysis and glycolytic enzymes such as LDHA might be key factors regulating chemoresistance of cancer cells." (PMID 35832094, 2022). "In addition, knockdown of LDHA can also have an effect on matrix metalloproteinases, thus affecting cancer cell invasion and metastasis." (PMID 36230492, 2022). "Furthermore, the DNP fraction was enriched with proteins relating to glycolysis and other metabolic pathways upregulated in cancer, including lactate dehydrogenase A (LDHA), transketolase, and β-hexosaminidase." (PMID 36310768, 2022). "Furthermore, we have shown recently that targeting the lactate/pyruvate metabolism in cancer cells by a pharmacological or genetic inhibition of LDHA/B results in decreased cytosolic Hsp90, Hsp70 and Hsp27 levels and a reduced membrane Hsp70 expression." (PMID 35463341, 2022). "High LDHA expression is related to the poor prognosis of malignant tumors." (PMID 36230492, 2022). "LDHA expression was found to be upregulated in cancer cells." (PMID 36497226, 2022). "The activation of LDHA may become a new therapeutic target due to it promotes the invasion and metastasis of cancer cells 26, and VEGFA is the main driver of angiogenesis and vascular permeability." (PMID 35711827, 2022). "Furthermore, genetic deletion of LDHA, 2-DG administration, or mTORC1 inhibition has been proposed as therapeutic avenues designed to decrease glycolytic metabolism in cancer cells, reduce lactate in the TIME, and repolarize TAMs to a pro-inflammatory state." (PMID 36072431, 2022). "LDHA phosphorylated at residue Tyr10 (pLDHA (Y10)) is found in a variety of human cancer cells." (PMID 36304460, 2022). "Therefore, several pharmacological LDHA inhibitors are being developed and tested as potential anti-cancer therapeutic agents." (PMID 35982980, 2022). "Activation of LDHA facilitates cancer cell invasion, anti-inflammation and metastasis." (PMID 36121916, 2022). "Increased HSF1 can act a rule as a transcription factor and cause evaluate the expression of lactate dehydrogenase A (LDHA), and oppositely reducing HSF1 can decrease the expression of LDHA, which targets one of the vital processes of cancer cells, which is actually glycolysis." (PMID 35990198, 2022). "LDHA performs a vital role in the glycolysis process in cancer, promotes cell proliferation, viability, invasion, angiogenesis, and metastasis, and allows cancer cells to evade the immune response." (PMID 36313570, 2022). "The LDHA isoform is frequently overexpressed in cancer and up-regulated by lncRNA-p21." (PMID 34298698, 2021).
cancer (continued). "Phosphorylation-mediated LDHA activation promoted cancer cell invasion and metastasis." (PMID 35127693, 2021). "Indeed, the LDHA isoform preferentially converts pyruvate to lactate, which is typical of cancer cells, while the LDHB isoform preferentially converts lactate to pyruvate." (PMID 34205977, 2021). "Moreover, miRNA-34a negatively regulates the expression of lactate dehydrogenase A (LDHA), which inhibits LDHA-dependent glucose uptake in cancer cells, as well as cell proliferation and invasion." (PMID 33540837, 2021). "LDHA, a key enzyme which catalyzes the formation of lactic acid from pyruvic acid, is a key gene in aerobic glycolysis and is widely seen as a therapeutic target for cancer." (PMID 33403045, 2021). "Moreover, tyrosine 10 (Y10) phosphorylation of LDHA, which is rampant in diverse cancers, is also correlated with several oncogenic tyrosine kinases, including fibroblast growth factor receptor 1 (FGFR1)." (PMID 34452627, 2021). "Targeting LDHA has also been investigated as a way to increase the aerobic metabolism of pyruvate within the mitochondria, increasing reactive oxygen species production, oxidative damage, and cancer cell apoptosis." (PMID 33718271, 2021). "Previous studies have reported that LDHA expression is increased in many human cancers." (PMID 34307169, 2021). "In addition, previous studies have indicated that several proteins, including glucose transporter 1 (GLUT1), hexokinase 2 (HK2), and lactate dehydrogenase A (LDHA), in glycolysis are often overexpressed in cancer." (PMID 34575112, 2021). "The abnormal expression of LDHA after siRNA treatment changed the expression of the cell cycle and apoptosis-related proteins and significantly reduced the migration and invasion ability of cancer cells." (PMID 34604067, 2021). "We observed a shift from the LDHB isoform to the LDHA isoform, which is typical of cancer cells." (PMID 34205977, 2021). "The results showed that LDHA was overexpressed in cancer tissues at the transcriptional level." (PMID 34743698, 2021). "The phosphorylation of LDHA is closely related to cancer development." (PMID 34604067, 2021). "The expression of LDHA in TCGA COAD RNA-seq dataset were analyzed by the Cancer RNASeq Nexus." (PMID 34307169, 2021). "Additionally, high expression of LDHA was observed in cancer tissues and was positively related to progression." (PMID 34743698, 2021). "Targeting LDHA to remodel the metabolic pathway has shown anticancer activity in cancer cells." (PMID 34235071, 2021). "Next, we analyzed LDHA mRNA expression in various human cancers using the TIMER database." (PMID 34307169, 2021). "Furthermore, UALCAN analysis showed that high expression of LDHA was closely related to cancer stage, nodal metastasis, and histological subtypes (p < 0.05)." (PMID 34307169, 2021). "LDHA has also been shown to be correlated with diverse immune cell infiltrations in cancers." (PMID 34307169, 2021). "Accumulating evidence indicates that LDHA inhibition not only exhibits promising anti-cancer effects through disrupting cellular energy metabolism, but also synergistically enhances the efficacy of other therapeutic regimens, including chemotherapy, radiotherapy and target drugs." (PMID 33902615, 2021). "Comparatively, glycolytic cancer cells generate lactate from pyruvate via the LDHA reaction." (PMID 34725423, 2021). "Previous studies have reported that LDHA (LDH5) plays a critical role in cancer." (PMID 34725423, 2021). "Metformin could change the metabolic status of cancer cells and reverse the Warburg effect via the inhibition of lactate dehydrogenase A(LDHA), which was overexpressed in CCA tissues and indicated a shorter survival time." (PMID 34745255, 2021). "Since the NAD+/NADH ratio plays a key role in redox homeostasis and cell proliferation, the CA as an LDHA inhibitor might affect the 5FU-resistant cancer cells through modulation of the NAD+/NADH ratio." (PMID 34065602, 2021).
cancer (continued). "LDHA inhibition was found to increase apoptosis of A549 cancer cells." (PMID 33718271, 2021). "In addition, LDHA is overexpressed in cancer cells that rely on aerobic glycolysis to maintain their higher proliferation and faster metabolic rates." (PMID 34575702, 2021). "However, we do see overlapping/similar pattern of staining for MB and CAIX in cancers and even more similar/identical sites were observed for MB and LDHA staining." (PMID 33996536, 2021). "Hence, LDHA is considered as a potential target for the prevention and treatment of cancers which depend on glycolysis and PPP." (PMID 35006438, 2021). "Based on the preferential use of lactate rather than glucose is a hallmark of many kinds of cancer, but the function of LDHA is still elusive." (PMID 33795650, 2021). "Thus, the radiosensitive effects of LDHA inhibition seems to be different in different cancer cells, efforts are still needed to identify predictive biomarkers and tested by clinical trials." (PMID 33902615, 2021). "This indicates that LDHA and its effect in hypoxic conditions is crucial for cancer cell survival." (PMID 32558023, 2020). "LDHA is aberrantly expressed in many cancers, including breast, kidney, lung, and ovarian cancers." (PMID 32806533, 2020). "Chemical approaches are among the common strategies to inhibit LDHA activity in cancer cells." (PMID 33199724, 2020). "Indeed, LDHA, PKM, and IDH2 are well-known players in the upregulation of cancer metabolism which are strongly associated with aggressive and invasive behavior of tumors and shortened patient’s survival." (PMID 33311447, 2020). "Inhibitors of lactate dehydrogenase A (LDH‐A), which are under development for cancer, may find complementary roles as immunomodulators." (PMID 32105390, 2020). "The combined application of CTX and oxalate showed a synergistic inhibition effect to inhibit the viability of CTX-resistant cells, suggesting that LDHA inhibition may be an effective sensitizer for the treatment of cancer resistance." (PMID 32038983, 2020). "Besides GLUT1, other key metabolic enzymes (e.g., HK1/2, PFKL, and LDHA) required for the glycolysis pathway of cancer cells were also investigated herein." (PMID 32774674, 2020). "LDHA was upregulated in most tumors and related to the poor prognosis of cancer." (PMID 33193873, 2020). "Interestingly, LDHA targeting has been reported to sensitize cancer cells to the cytotoxic effects of chemotherapy, including paclitaxel-resistant BrCa cells." (PMID 33339207, 2020). "Therefore, we compared the expression of LDHA in cancer and adjacent normal tissues of the seven patients." (PMID 32859246, 2020). "Furthermore, high-level LDHA expression serves as a prognostic indicator in patients with different cancers." (PMID 33153193, 2020). "However, in various cancer cell lines, the LDHA isoform is highly expressed because LDHA prefers the pyruvate to lactate transition." (PMID 33081387, 2020). "Besides, upregulation of key proteins involved in lactate metabolism, namely LDHA and MCTs, have demonstrated clinical prognostic value and are seen as rational targets for cancer therapy." (PMID 32257942, 2020). "Besides serum LDH, LDHA levels in cancer tissues have been reported as a biomarker of malignancy and prognosis." (PMID 32257942, 2020). "In cancer cells, KRAS mutation induces transcription of genes encoding key enzymes of anabolic glucose metabolism, including glucose transporter 1, hexokinases, phosphofructokinase 1, and lactate dehydrogenase A." (PMID 32481524, 2020). "Besides prognostic biomarkers, both LDHA and MCTs have been recognized as attractive targets for cancer therapy." (PMID 32257942, 2020).
cancer (continued). "LDHA is found in human cancers at higher levels compared to normal tissues and plays an important role in the development, invasion, and metastasis of some types of cancer." (PMID 33233671, 2020). "These compounds include 1,3-benzodioxole derivatives, such as Machilin A, which are efficient competitive inhibitors that function by blocking the nicotinamide adenine dinucleotide (NAD) binding site of LDHA, suppressing lactate production and cancer cell growth." (PMID 33199724, 2020). "However, in cancer cells, pyruvate transport into mitochondria is limited because cancer cells have higher expression of lactate dehydrogenase (LDHA), which catalyzes pyruvate to lactate, compared with normal cells." (PMID 33238375, 2020). "As cancer cells accelerated glycolysis generally by preferential expression of glucose transporters (e.g., Glut1) and key glycolytic enzymes (e.g., HK II and LDHA)." (PMID 32093118, 2020). "Furthermore, inhibition of LDHA expression or inhibition of its activity suppresses cancer cell growth in vitro and in vivo." (PMID 31471554, 2019). "LDHA was critical for the glucose metabolism of cancer cells." (PMID 31850191, 2019). "Additionally, it has been established that upregulation of LDHA significantly contributes to increased glycolysis in various cancers, however, how LDHB is regulated is poorly understood." (PMID 31804482, 2019). "Taken together, these findings show that lowering of LDHA by vitamin C reduces tumorigenicity and that vitamin C might be a novel and effective therapeutic agent for targeting cancer in patients undergoing chronic stress." (PMID 30688660, 2019). "In addition, LDHA inhibition, which is primarily expressed in cancer cells, has also emerged as an attractive potential method of clinical intervention." (PMID 31159361, 2019). "Thus, MA inhibited cancer growth and energy metabolism by inhibiting the activity of LDHA in cancer cells both under normoxic and hypoxic conditions." (PMID 31324019, 2019). "Furthermore, because the expression of LDHA in human cancer tissues is higher than that in normal tissues, LDHA is considered a promising target for cancer diagnosis and therapy." (PMID 30926903, 2019). "All of these changes indicate that LDHA silencing or using an LDHA inhibitor induces an apoptosis ratio in cancer cells via the mitochondrial pathway, measured by the percentage of apoptotic cells (~3.3-fold increase; p < 0.001) or by estimating the sub-G1 cell fraction." (PMID 31035592, 2019). "GNE-140 is a selective LDHA inhibitor of nano-molar potency but if it is removed from the medium, cells can proliferate even after 2 d of continuous inhibition which implies that sustained inhibition is needed for long-term cancer cell control." (PMID 31835667, 2019). "Pyruvate produced through glycolysis is further metabolized to lactate rather than to acetyl coenzyme A (acetyl-CoA) through lactic acid fermentation mediated by lactate dehydrogenase A (LDH-A) in cancer cells expressing high levels of LDH-A in a HIF-1-dependent manner." (PMID 30634433, 2019). "Thus, the enhanced production of LDH-5 with four LDHA subunits in cancer cells leads to an increase in the glycolytic metabolism in the presence or absence of oxygen." (PMID 31324019, 2019). "The aberrant activation of GLCC1/c-Myc/LDHA glycolysis cascade might be cancer’s comprehensive metabolic adaptation to allow cancer cells to survive from glucose starvation." (PMID 31375671, 2019). "As LDHA is a key enzyme for aerobic glycolysis, one of characteristic features of malignant tumors, it has been regarded as an attractive molecular target for cancer inhibition." (PMID 30850682, 2019). "From these results, we suggest that MA, a novel LDHA inhibitor, may be candidates for anti-cancer drugs." (PMID 31324019, 2019). "Moreover, Y10 phosphorylation of LDHA is common in diverse human cancer cells attributed to the activation of multiple oncogenic tyrosine kinases." (PMID 30886157, 2019).
cancer (continued). "Interestingly, MA prohibited NADH from binding and inhibiting LDHA, and therefore inhibited growth of various cancer cell types." (PMID 31324019, 2019). "LDHA is an essential enzyme in aerobic glycolysis of cancer cells." (PMID 31523182, 2019). "LDHA inhibition, in particular, is currently being tested as a potential anti-cancer strategy in pre-clinical studies and upcoming results could very well prove the clinical viability of LDHA inhibitors." (PMID 31159361, 2019). "Additionally, the upregulation of LDHA enhances lactate production by aerobic glycolysis, which provides sufficient biomaterials and energy for the growth and metabolism of cancer cells." (PMID 31921691, 2019). "However, the inhibition of LDHA only rather impair cell growth and tumorigenesis in the context of cancer." (PMID 31483850, 2019). "In recent years, numerous studies have reported that LDHA knockdown could suppress the growth and metastasis of cancer cells." (PMID 31921691, 2019). "Furthermore, it is known that the levels of LDHA expression are higher in many cancers than in normal tissues." (PMID 31324019, 2019). "Taken together, these observations suggest that interventions to reverse the Warburg effect, such as the inhibition of LDHA, may harm cancer cells by depriving them of these survival mechanisms." (PMID 30813322, 2019). "Finally, these results demonstrate for the first time that CK2α mediates LDHA expression and increases migration as well as invasion in human cancer cells." (PMID 30926903, 2019). "It has been shown that human epidermal growth factor receptor 2 (HER2) and avian sarcoma viral oncogene v-src homolog (SRC) activate LDHA through phosphorylation at tyrosine 10 residue which further results in pro-invasive and pro-metastatic behavior of cancer cells." (PMID 31146503, 2019). "Given the importance of lactate metabolism in different types of cancers, the discovery and development of new molecules that could inhibit LDHA activity is urgently needed." (PMID 31737570, 2019). "Lactate dehydrogenase A plays an important role in metabolic pathways of the cancer cells." (PMID 30886157, 2019). "Moreover, MA significantly suppressed the growth of several cancer cells, based on the inhibition of LDHA activity." (PMID 31324019, 2019). "Therefore, LDHA has been the target of different miRNAs in cancer cells to regulate the tumorigenesis." (PMID 31850191, 2019). "LDHA promotes cancer progression by regulating epithelial-to-mesenchymal transition (EMT) related genes such as Snail, Slug, E cadherin, N-cadherin, Fibronectin, Vimentin and by upregulating expression of stemness related genes such as OCT4, SOX2, Nanog and c-Myc." (PMID 31146503, 2019). "Interestingly, Tyr10-phosphorylation by upstream kinases, HER2 and Src is needed for LDHA activation, and provides pro-invasive, antianoikis and prometastatic values to cancer cells." (PMID 31035592, 2019). "Given the high demand for ATP as “fuel” and metabolic intermediates as “building blocks” in cancer cells, aberrant proliferation generally accompanied with enhanced ROS production, suggesting that the mechanism of LDHA nuclear translocation is potentially ubiquitous." (PMID 30356100, 2018). "Additionally, LDHA expression is increased in multiple types of cancer, likely driven by c-myc and HIF-1 overexpression." (PMID 30087897, 2018). "However, both types of resistant cells did exhibit a marked reliance on LDHA activity, thus pointing to this enzyme as a crucial crossroad for cancer cell survival and as a new anticancer target." (PMID 29541451, 2018). "In this review, we summarized LDHA function in cancer research." (PMID 30403008, 2018). "In addition, a natural extract with the ability to inhibit LDHA, named gall, has also been found to be very effective in cancer treatment." (PMID 30403008, 2018). "In cancers, enhanced LDHA promotes diverse malignant bio‐characteristics." (PMID 30403008, 2018).